DPP4 (dipeptidyl peptidase 4)
Diseases named in the same sentence as DPP4 in open-access papers (continued):
Sharing a sentence is not in itself a finding about the gene and the disease.
breast carcinoma (continued). "Recently, DPP4/CD26 was identified as a new marker for cancer-associated fibroblasts (CAFs), and its expression has been reported to increase with breast cancer progression." (PMID 37218983, 2023). "Our findings identify a novel role for DPP-4 inhibition in the promotion of breast cancer survival by inducing CXCL12/CXCR4/mTOR/HIF-1α axis-dependent autophagy." (PMID 37760498, 2023). "To assess the effect of metformin on DPP-4 inhibitor-induced breast cancer autophagy and survival, we performed IHC staining in 4T1 primary tumors." (PMID 37760498, 2023). "Our results in this study and Yang’s report showed the promoted effect of DPP4 knockdown on OV cell lines and 4 T-1 (breast cancer cell line) cell migration respectively." (PMID 37907650, 2023). "Next, we evaluated the effect of DPP-4 suppression on the cell proliferation rate in human normal epithelial and breast cancer cells." (PMID 37760498, 2023). "The proteomics data particularly distinguished 29 upregulated proteins, such as GSS, GOT1, GPX3, and LDHB, and two downregulated proteins, including GC and dipeptidyl peptidase 4 (DPP4), in breast cancer." (PMID 37509485, 2023). "In the investigation of HCC and breast cancer using syngeneic mouse models, Hollande and colleagues found that inhibition of DPP-4 increased the migration of eosinophils into solid tumors and reduced tumor growth." (PMID 35933633, 2022). "Other notable examples include Dipeptidyl peptidase 4 (DPP4), a membrane-bound extracellular glycoprotein with a function to facilitate breast cancer cell adhesion in rats." (PMID 36589798, 2022). "In syngeneic mouse models of hepatocellular carcinoma and breast cancer, additional treatment with an antidiabetic drug, the dipeptidyl peptidase 4 (DPP4) inhibitor sitagliptin, was shown to promote intratumoral recruitment of eosinophils." (PMID 36428768, 2022). "Metformin also suppressed dipeptidyl peptidase-4 (DPP-4) inhibitor-induced EMT via the suppression of mechanistic target of rapamycin (mTOR) signaling in breast cancer." (PMID 34399790, 2021). "With regard to this finding, we have shown that the DPP-4 inhibitor induces breast cancer metastasis and chemoresistance via an increase in its substrate C-X-C motif chemokine 12, and the consequent induction of epithelial-mesenchymal transition in the tumor." (PMID 34063285, 2021). "DPP-4 inhibitor-induced breast cancer metastasis was attenuated by the CXCR4 inhibitor AMD3100, with the suppression of genes associated with EMT and a mammalian target of rapamycin (mTOR) signaling pathway in the primary tumor." (PMID 34063285, 2021). "In a mouse model of breast cancer, inhibition of DPP-4 promoted metastasis formation, while metformin had an inhibitory effect on it by influencing mTOR-related signals." (PMID 34778040, 2021). "Rats treated with sitagliptin had decreased precancerous lesions and reactive oxygen species in a colon cancer in vivo model, and DPP4 inhibition with sitagliptin suppressed tumour growth in a 4T1 syngeneic model of breast cancer." (PMID 33513866, 2021). "The results demonstrated that ACO1, DPP4, HMOX1, and TFRC were significantly associated with breast cancer grades (all p < 0.05)." (PMID 35154262, 2021). "Eventually, CORO1A and ANXA5 as the representative target genes for breast cancer and DPP4 for prostate cancer were made the following analysis." (PMID 33407865, 2021). "The tumor-promoting role of DPP4 has also been reported, as aberrant expression of DPP4 is frequently observed in hepatocellular, colorectal, and breast cancer." (PMID 34926239, 2021). "We also found that the DPP-4 inhibitor induces breast cancer metastasis via the inhibition of CXCL12 degradation." (PMID 34063285, 2021). "Results from an Oncomine analysis showed that mRNA expression levels of DPP3 and DPP9 were highly upregulated in breast cancer tissues, whereas DPP4, DPP6, and DPP8 exhibited downregulated levels in breast cancer tissues relative to normal breast tissues." (PMID 34359286, 2021).
breast carcinoma (continued). "We have recently reported that metformin mitigates DPP-4 inhibitor-induced breast cancer EMT and metastasis via the suppression of mTOR activation." (PMID 34063285, 2021). "We also showed that DPP-4 ablation in a primary mammary tumor induced tumor growth and metastasis via the CXCL12-mediated pathway." (PMID 34063285, 2021). "Apart from colorectal and lung cancer, CD26/DPP4 protein is well-expressed in prostate cancer cells, while its expression in pancreatic or breast cancer cells is relatively lower." (PMID 32296640, 2020). "DPP-4 has been shown to be involved in cancer biology, and we have recently shown that a DPP-4 inhibitor promoted the epithelial mesenchymal transition (EMT) in breast cancer cells." (PMID 31991851, 2020). "In our previous study, we have confirmed that DPP-4 inhibition induced the EMT through the CXCL12/CXCR4/mTOR axis in breast cancer." (PMID 31991851, 2020). "To explore the effects of DPP-4 suppression on chemoresistance in breast cancer cells, we utilized the DPP-4 inhibitor KR62436 or DPP-4 knockdown by specific shRNA (DPP-4-kd) in 4T1 cells." (PMID 31991851, 2020). "Taken together, our findings suggest that DPP-4 inhibitors potentiate chemotherapy resistance via the induction of ABC transporters by the CXCL12/CXCR4/mTOR/TGFβ signaling pathway in breast cancer cells." (PMID 31991851, 2020). "In our previous study, we demonstrated that deficiency in DPP-4 induced EMT in 4T1 cells, MCF-7 cells and MDA-MB-231 cells and accelerated lung metastasis of breast cancer in vivo via the CXCL12/CXCR4/mTOR axis." (PMID 31991851, 2020). "In the preclinical mouse model of hepatic, prostate and breast cancer, inhibition of the dipeptidyl-peptidase 4 (DPP4) with the FDA approved drug sitagliptin enhances host eosinophil-mediated antitumoral activity and contribute to ICB efficacy." (PMID 32580431, 2020). "DPP4 is identified as a pivotal enzyme in regulating sICOSL levels in breast cancer." (PMID 40708008, 2025). "DPP4 inhibition (using the anti-diabetic medication, sitagliptin) in a pre-clinical syngeneic mouse model of breast cancer has been shown to increase CCL11 levels, eosinophil infiltration and improve tumor control and was synergistic with immune checkpoint inhibition." (PMID 40428397, 2025). "Our results also revealed that DPP4/CD26 could be a novel marker used to detect senescent breast cancer cells, which could be targeted using azithromycin treatment." (PMID 38786063, 2024). "This BrdU-induced increase in DPP4/CD26 expression could also be detected in other breast cancer cell lines, which indicates that it could be a potential marker of senescence in breast cancer." (PMID 38786063, 2024). "However, metformin, known for its inhibition of the mTOR signaling pathway, was suggested to counteract the unfavorable effects of DPP-4 inhibitors on breast cancer metastasis by suppressing mTOR, indicating its potential clinical relevance." (PMID 38254789, 2024). "Finally, we found that metformin inhibited the DPP-4 deficiency-stimulated mTOR/HIF-1α/autophagy axis and induced breast cancer apoptosis." (PMID 37760498, 2023). "Western blotting showed that DPP-4 inhibition decreased the levels of cleaved caspase-3, an apoptosis-associated protein, in the human MCF7 and MDA-MB-231 breast cancer cell lines; however, the autophagy inhibitor 3-methyladenine (3-MA) remarkably restored the levels of cleaved caspase-3." (PMID 37760498, 2023). "DPP-4 inhibition may induce differential responses in autophagy and cell survival between breast cancer cells and normal cells." (PMID 37760498, 2023). "Altogether, DPP-4 inhibition could influence cell survival via the augmentation of autophagy in breast cancer cells." (PMID 37760498, 2023).
breast carcinoma (continued). "The CXCR4 inhibitor treatment decreased the KR-induced gene expression profile and breast cancer progression when compared to that of the KR alone group, suggesting that mTOR pathway activation is relevant for DPP-4 inhibitor-mediated breast cancer progression." (PMID 37760498, 2023). "Furthermore, DPP-4 deficiency-augmented autophagy is crucial for the survival advantage in breast cancer cells treated with a DPP-4 inhibitor." (PMID 37760498, 2023). "Regarding this hypothesis, we have shown that metformin failed to suppress basal tumor growth in 4T1-bearing mice, but suppressed both growth and phosphorylated-mTOR/S6K levels in 4T1 mammary tumors, but only when co-administered with a DPP-4 inhibitor." (PMID 37760498, 2023). "In addition, computational prediction indicated that DPP4 was down-regulated in breast cancer, TF was down-regulated in other tumors and ZFP69B was up-regulated in other tumors." (PMID 36568247, 2022). "Furthermore, the stroma of human breast cancer presents less DPP4 expression than normal breast tissues, and the suppression of DPP4 promotes cancer metastasis via CXCL12 signaling." (PMID 35300413, 2022). "Interestingly, our data demonstrated that DPP4 had low expression levels in breast cancer tissues at both the transcription and protein levels, but was associated with poor prognoses in breast cancer patients." (PMID 34359286, 2021). "Here, we hypothesize that DPP-4 inhibition increases ABC transporters in the presence of chemotherapy to promote drug resistance in breast cancer." (PMID 31991851, 2020). "Notably, paclitaxel decreased DPP4 expression only in tumor cells of primary breast cancer." (PMID 40708008, 2025). "And whether DPP4 influences breast cancer progression through m6A requires further investigation." (PMID 41357233, 2025). "They reported that the influence of DPP-4 inhibitors on the risk of breast cancer was not significant in the results of randomized controlled trials (RR = 0.74, 95% CI: 0.36–1.52), but that in the results of observational analysis, such risk is decreased (HR = 0.76, 95% CI: 0.60–0.96)." (PMID 38254789, 2024). "We also examined the gene dipeptidyl petidease-4 (DPP4/CD26), a close homologue to FAPα, which was recently identified as a fibroblast marker of interlobular fibroblasts in healthy breast tissue and shown to display immune suppressive functions in breast cancer." (PMID 34016130, 2021). "Therefore, metformin may have more anti-tumor influence on a mammary tumor when co-prescribed with DPP-4 inhibitors, compared with metformin alone." (PMID 34063285, 2021). "Similarly, the role of CD26/DPP4 in breast cancer remains poorly understood." (PMID 32296640, 2020). "Our recent study also demonstrated that DPP-4 inhibitor could induce EMT in breast cancer cells." (PMID 31101909, 2019). "Breast cancer patients with high EZH2, ICOSLG expression and low DPP4 expresssion had potentially stronger ability to release sICOSL, and thus a significant adverse overall survival." (PMID 40708008, 2025). "According to one study in breast cancer patients, based on the expression of specific markers CD29, FAP, FSP1, α-SMA, CAV-1 and dipeptidylpeptidase 4 (DPP-4, CD26), CAFs can be classified into four subtypes: CAFs-S1 to S4." (PMID 40940764, 2025). "Therefore, we speculated that EZH2 inhibited DPP4 expression in the breast cancer." (PMID 40708008, 2025). "Then, we developed a risk prognostic model based on expression levels of PIK3CA, SESN3, ANXA5, MYD88, DPP4, DAXX, and CRIP1 to predict clinical outcomes in patients with breast cancer." (PMID 41357233, 2025). "Further analysis revealed that when recombinant DPP4 was co-incubated directly with breast cancer cells and subsequently analyzed by flow cytometry using an anti-ICOSL antibody, the level of mICOSL remained unaffected by the concentration of DPP4." (PMID 40708008, 2025).
breast carcinoma (continued). "In human breast cancer (BC), CAF-S1 drives recruitment and subsequent differentiation of CD25+FOXP3+ regulatory T cells (Treg) through the engagement of surface B7H3, DPP4, and CD73 signaling." (PMID 41583489, 2025). "We investigated the role of a novel senescence marker (DPP4/CD26) and a senolytic drug (azithromycin) on the senescence-escaping ability of MCF-7 and MDA-MB-231 breast cancer cells." (PMID 38786063, 2024). "By using this method, we investigated the effect of a novel senescence marker (DPP4/CD26) and a senolytic drug (azithromycin) on the senescence-escaping ability of breast cancer cells." (PMID 38786063, 2024). "DPP-4 knockdown significantly promoted the levels of CXCL12, CXCR4, phospho-mTOR, and HIF-1α in breast cancer cell lines." (PMID 37760498, 2023). "However, in breast cancer, DPP4+ASCs do not serve as an independent risk factor for survival." (PMID 37454080, 2023). "A dipeptidyl peptidase (DPP)-4 inhibitor accelerated breast cancer metastasis by inducing EMT through CXCL12/CXCR4/mTOR axis, while metformin countered the harmful effect of DPP-4 inhibitor on breast cancer metastasis." (PMID 37497001, 2023). "DPP-4 suppression augmented CXCL12/CXCR4 levels, which led to autophagy and HIF-1α in breast cancer cells; a CXCR4 inhibitor reversed these DPP-4 inhibition-induced alterations." (PMID 37760498, 2023). "In conclusion, we show here that DPP-4 inhibition accelerates breast cancer cell survival by inducing autophagy through CXCL12/CXCR4-mediated mTOR/HIF-1α activation; metformin abrogates such alterations induced by DPP-4 suppression." (PMID 37760498, 2023). "DPP-4 knockdown and DPP-4 inhibitor KR62436 (KR) treatment both increased the levels of LC3II and HIF-1α in cultured human breast and mouse mammary cancer cells." (PMID 37760498, 2023). "For metformin, the highest number of its targets were associated with malignant neoplasm of the prostate (six genes) and breast carcinoma (seven genes: ABCB11; ABCC2; ABCC3; ABCC4; DHFR; DPP4; SLC22A1)." (PMID 36046822, 2022). "Inhibition of dipeptidyl peptidase (DPP)-4 stimulated CXCL12/CXCR4 expression and activated mTOR signaling, which further induced epithelial-mesenchymal transition of breast cancer cells and metastasis." (PMID 34234860, 2021). "With regard to this, we have reported that the DPP-4 inhibitor increases ABC transporters via EMT induction, resulting in breast cancer chemoresistance." (PMID 34063285, 2021). "We have recently shown that a DPP-4 inhibitor accelerated the epithelial mesenchymal transition (EMT) and lung metastasis via the CXCL12/CXCR4/mTOR axis in breast cancer cells." (PMID 31991851, 2020). "Preliminary support is available from demonstrations that FAP-positive S1 breast cancer fibroblasts promote the formation of FoxP3-positive T cells in a manner involving B7H3, CD73 and DPP4." (PMID 33153037, 2020). "We aim to study the impact of DPP4 inhibitors (DPP4i) in patients with prostate cancer (PRC), pancreatic cancer (PC) and breast cancer (BC)." (PMID 32296640, 2020). "Gene targets in breast cancer samples, including CYP24A1, DPP4 and CA2, seem to be shared by both fibroblasts and epithelial cells." (PMID 23497279, 2013). "So chemotherapy downregulated total DPP4 in breast cancer possibly through inhibiting protein expression rather than by blocking enzyme activity." (PMID 40708008, 2025). "Similarly, in breast cancer, FAP‐positive (FAP+) CAFs demonstrated peritumoral and perivascular localization, with dipeptidyl peptidase 4 (DPP4)/YAP1‐driven plasticity linking their distribution to immune exclusion and invasion." (PMID 40656546, 2025). "Immunohistochemistry data from the Protein Atlas indicate moderate to strong CD26/DPP-4 expression in prostate cancers, a characteristic absent in most other cancers, including pancreatic and breast cancers." (PMID 40282969, 2025).
breast carcinoma (continued). "Notably, another protease, dipeptidyl peptidase 4 (DPP4), was significantly enriched in breast cancers with low sICOSL levels." (PMID 40708008, 2025). "Moreover, the expression levels of SESN3, CRIP1, DPP4 and PIK3CA were significantly upregulated in breast cancer samples compared to control samples." (PMID 41357233, 2025). "Some studies even found a reduced risk of breast cancer in diabetic patients treated with SGLT2i vs. DPP-4 inhibitors (HR: 0.51, p < 0.001) or vs. non-SGLT2i users (HR: 0.77, p = 0.001), and reduced breast cancer mortality in SGLT2i users vs. non-users." (PMID 39941833, 2025). "In summary, DPP4 specifically mediated the degradation of sICOSL rather than mICOSL in the breast cancer microenvironment." (PMID 40708008, 2025). "For instance, investigations into breast cancer did not demonstrate significant survival advantages in patients treated with DPP-4 inhibitors." (PMID 39595655, 2024). "Dipeptidyl peptidase IV (DPP4/CD26) was identified as a cell surface marker for senescent fibroblast cells; however, it has not been validated in other cell types, such as in breast cancer cells." (PMID 38786063, 2024). "Regarding the pleiotropic effects of DPP-4 inhibitors on cancer biology, we have previously shown that DPP-4 suppression accelerates breast cancer metastasis by inducing EMT through C-X-C motif chemokine 12 (CXCL12)/C-X-C receptor 4 (CXCR4)-mediated mTOR activation." (PMID 37760498, 2023). "The current data also indicated that mTOR/HIF-1α is a dominant pathway for DPP-4 inhibition-induced autophagy in breast cancer cells, but not in normal breast epithelial cells." (PMID 37760498, 2023). "The level of mTORC2 downstream AKT phosphorylation was not altered by KR treatment, indicating that DPP-4 suppression targets the mTORC1 pathway rather than mTORC2 in breast cancer cells." (PMID 37760498, 2023). "The Kaplan–Meier (KM) plot showed that high expression levels of DPP3 and DPP4 were correlated with poor survival of breast cancer patients, whereas other DPP family members were not." (PMID 34359286, 2021). "In addition, CXCL12 inhibits DPP4 and accelerates EMT and metastasis in breast cancer, and the inhibition of ERBB3 signaling suppresses EMT of hepatocellular carcinoma." (PMID 33463049, 2021). "In addition, four cytokeratin genes (KRT8, KRT16, KRT17, and KRT19) and eight tumor-associated genes (TERT, MUC16/M17S2/CA125, CD44, TWIST1, TACSTD1/EpCAM/CD326/ESA/HEA125/GA733, DPP4/CD26, ESR1, and PGR), were upregulated in CRC and breast cancer samples." (PMID 29882767, 2018). "In addition, DPP4 and ICOS expression were positively correlated in both breast cancer cohorts." (PMID 40708008, 2025). "Similar findings were reported in breast cancer where different subsets of CAF were also identified, and where CAF-S1 enhanced Treg cell polarization through the expression of the adenosine ectonucleotidase CD73 and the inhibitory molecules B7 Homolog 3 (B7H3) and dipeptidyl peptidase-4 (DPP4)." (PMID 35892828, 2022). "In addition, the possible ferroptosis mechanisms of CDKN2A, PSAT1, SLC7A11, LAMP2, CAV1, and HMGB1 in TNBC and ASNS, ZFP69B, ELAVL1, TF, HELLS, and DPP4 in breast cancer have not been reported." (PMID 36568247, 2022). "Interestingly, our preclinical data demonstrated that metformin represents anti-tumor/anti-metastatic effect only when prescribed with a DPP-4 inhibitor; nevertheless, metformin alone had no impact on basal breast cancer proliferation and metastasis in vivo." (PMID 34063285, 2021). "We found that the expression of DPP4/CD26 was significantly increased in BrdU-, GEM- and PALBO-induced senescent MCF-7 and MDA-MB-231 cells and in BrdU-treated breast cancer cell lines (CAMA-1, MDA-MB-468 and T47D), indicating that it could be a potential new marker of senescence in breast cancer." (PMID 38786063, 2024).